HIF1A (hypoxia inducible factor 1 subunit alpha)
Description:
Functions as a master transcriptional regulator of the adaptive response to hypoxia. Under hypoxic conditions, activates the transcription of over 40 genes, including erythropoietin, glucose transporters, glycolytic enzymes, vascular endothelial growth factor, HILPDA, and other genes whose protein products increase oxygen delivery or facilitate metabolic adaptation to hypoxia. Plays an essential role in embryonic vascularization, tumor angiogenesis and pathophysiology of ischemic disease. Heterodimerizes with ARNT; heterodimer binds to core DNA sequence 5'-TACGTG-3' within the hypoxia response element (HRE) of target gene promoters (By similarity). Activation requires recruitment of transcriptional coactivators such as CREBBP and EP300. Activity is enhanced by interaction with NCOA1 and/or NCOA2. Interaction with redox regulatory protein APEX1 seems to activate CTAD and potentiates activation by NCOA1 and CREBBP. Involved in the axonal distribution and transport of mitochondria in neurons during hypoxia. (Microbial infection) Upon infection by human coronavirus SARS-CoV-2, is required for induction of glycolysis in monocytes and the consequent pro-inflammatory state. In monocytes, induces expression of ACE2 and cytokines such as IL1B, TNF, IL6, and interferons. Promotes human coronavirus SARS-CoV-2 replication and monocyte inflammatory response.
Synonyms: HIF-1-alpha; HIF1-alpha; bHLHe78; MOP1; PASD8; HIF-1alpha; HIF1; HIF-1A
Tractability: Small molecule: a structure with a bound ligand is known; a high-quality ligand is known; it belongs to a druggable protein family. PROTAC: UniProt records ubiquitination sites on it; ubiquitination databases record sites on it; a small molecule that binds it is known.
Target class: Transcription factor
Safety:
Unwanted effects reported when the protein is acted on. In parentheses: how it was acted on, where the effect was seen, and who reports it.
Decrease, Population growth rate (activation; source: AOP-Wiki)
Reduction, Cumulative fecundity and spawning (activation; source: AOP-Wiki)
Liver Cancer (activation; source: AOP-Wiki)
Increase, Early Life Stage Mortality (source: AOP-Wiki)
Gene: Protein-coding gene on chromosome 14 (61,695,456 to 61,748,263, forward strand). Ensembl gene ENSG00000100644.
Subcellular location: Cytoplasm; Nucleus; Nucleus speckle
Subcellular location (Human Protein Atlas): Nuclear bodies; Nucleoplasm
Pathways (Reactome):
Signal Transduction: NOTCH1 Intracellular Domain Regulates Transcription; PTK6 Expression; PTK6 promotes HIF1A stabilization; STAT3 nuclear events downstream of ALK signaling
Cellular responses to stimuli: Cellular response to hypoxia; Oxygen-dependent proline hydroxylation of Hypoxia-inducible Factor Alpha; Regulation of gene expression by Hypoxia-inducible Factor
Immune System: Interleukin-4 and Interleukin-13 signaling; Regulation of PD-L1(CD274) transcription
Metabolism of proteins: Neddylation; Ub-specific processing proteases
Gene Ontology:
Molecular function: cis-regulatory region sequence-specific DNA binding; DNA-binding transcription activator activity; DNA-binding transcription activator activity, RNA polymerase II-specific; DNA-binding transcription factor activity; DNA-binding transcription factor activity, RNA polymerase II-specific; DNA-binding transcription repressor activity; enzyme binding; histone deacetylase binding; Hsp90 protein binding; nuclear receptor binding; protein binding; protein domain specific binding; protein heterodimerization activity; protein kinase binding; RNA polymerase II cis-regulatory region sequence-specific DNA binding; RNA polymerase II transcription regulatory region sequence-specific DNA binding; RNA polymerase II-specific DNA-binding transcription factor binding; sequence-specific DNA binding; transcription coactivator binding; transcription corepressor binding; transcription regulator activator activity; ubiquitin protein ligase binding; DNA binding; E-box binding; and 1 more
Biological process: axonal transport of mitochondrion; cellular response to hypoxia; cellular response to interleukin-1; cellular response to oxidative stress; cellular response to virus; intracellular glucose homeostasis; intracellular oxygen homeostasis; negative regulation of gene expression; negative regulation of miRNA transcription; negative regulation of oxidative stress-induced neuron intrinsic apoptotic signaling pathway; positive regulation of angiogenesis; positive regulation of blood vessel endothelial cell migration; positive regulation of chemokine-mediated signaling pathway; positive regulation of cytokine production involved in inflammatory response; positive regulation of DNA-templated transcription; positive regulation of gene expression; positive regulation of glycolytic process; positive regulation of hormone biosynthetic process; positive regulation of miRNA transcription; positive regulation of transcription by RNA polymerase II; positive regulation of vascular endothelial growth factor production; regulation of DNA-templated transcription; regulation of gene expression; regulation of glycolytic process; regulation of protein neddylation; and 18 more
Cellular component: chromatin; cytoplasm; cytosol; nuclear body; nucleoplasm; nucleus; protein-containing complex; RNA polymerase II transcription regulator complex; nuclear speck; transcription regulator complex; axon cytoplasm; euchromatin; motile cilium
Genetic constraint (gnomAD): Loss-of-function variants: 10 observed, 48.11 expected, observed/expected ratio (o/e) 0.21, 90% interval 0.13 to 0.35. The upper end of that interval is the gene's LOEUF score, 0.35, which puts it in group 1 of 6, group 1 being the genes least tolerant of losing a copy. Missense variants: 549 observed, 708.27 expected, observed/expected ratio (o/e) 0.78, 90% interval 0.72 to 0.83. Synonymous variants: 229 observed, 250.36 expected, observed/expected ratio (o/e) 0.91, 90% interval 0.82 to 1.02.
Cancer hallmarks: angiogenesis (promotes); escaping programmed cell death (promotes); invasion and metastasis (promotes); change of cellular energetics (promotes); escaping immune response to cancer (promotes)
Homologues: Orthologues: macaque HIF1A (99% identical), chimpanzee HIF1A (99% identical), dog HIF1A (96% identical), pig HIF1A (95% identical), guinea pig HIF1A (94% identical), rabbit HIF1A (92% identical), mouse Hif1a (90% identical), rat Hif1a (90% identical), tropical clawed frog hif1a (68% identical), zebrafish hif1ab (58% identical), Drosophila melanogaster sima (33% identical), Drosophila melanogaster trh (22% identical), and 1 more. Paralogues in human: EPAS1 (46% identical), HIF3A (31% identical), NPAS3 (24% identical), SIM2 (22% identical), SIM1 (22% identical), NPAS1 (18% identical), NPAS4 (16% identical).
Diseases named in the same sentence as HIF1A in open-access papers:
HIF1A is named in the same sentence as 1,003 diseases in open-access papers, as found by Europe PMC text mining. Sharing a sentence is not in itself a finding about the gene and the disease. The quoted sentences say what the papers report.
breast cancer (1,393 papers, 2004 to 2026). A primary or metastatic malignant neoplasm involving the breast. "For example, berberine, an isoquinoline alkaloid, has been reported to reduce HIF-1α expression at both the mRNA and protein levels and to suppress hypoxia-associated phenotypes in breast cancer cells." (PMID 41614951, 2026). "Tamoxifen treatment can cause lncRNA UCA1 expression to be upregulated in breast cancer cell lines in a way that is dependent on HIF-1α." (PMID 41614928, 2026). "Downregulation of miRNAs in CAF-derived exosomes promotes breast cancer malignancy, with loss of miR-7641 enhancing stemness and glycolysis by upregulating HIF-1α in cancer cells." (PMID 40230452, 2025). "HIF-2α, while less studied than HIF-1α, also contributes to tumor progression and is often associated with more aggressive breast cancer subtypes." (PMID 40901111, 2025). "For example, the overexpression of HIF-1α has been associated with aggressive tumor behavior, poor prognosis, and resistance to therapy in breast cancer patients." (PMID 40901111, 2025). "Background/Objectives: HIF-1α and ERRα are both implicated in breast cancer progression, yet their functional interplay remains poorly understood." (PMID 40723264, 2025). "Overexpression of HIF-1α is often associated with aggressive breast cancer phenotypes and poor prognosis." (PMID 40901111, 2025). "Increased tumor HIF-1α levels were associated with a decreased overall response to epirubicin in patients with breast cancer and with an overexpression of several genes sustaining angiogenesis, and drug resistance." (PMID 39863855, 2025). "Simultaneously, high expression of HIF-1α is associated with higher mortality in multiple cancers, such as breast cancer and hepatocellular carcinoma." (PMID 39757165, 2025). "In the presented work we analysed TCGA data, exploring how the WWOX/HIF1A ratio is associated with differentiation of tumour transcriptomes of breast cancer, hepatocellular carcinoma, and brain tumours." (PMID 41007296, 2025). "While previous reports have separately linked ERRα and HIF-1α to hypoxic responses, our work uniquely demonstrates their interconnected activity in a 3D spheroid model of breast cancer." (PMID 40723264, 2025). "LOX expression is positively correlated with matrix metalloproteinases (MMPs) and hypoxia-inducible factor 1α (HIF-1α), both of which are linked to breast cancer invasion and metastasis." (PMID 39247609, 2024). "This protein appears to be downregulated in human breast cancer, and this is associated with an increased expression of HIF1-α target genes." (PMID 38790264, 2024). "Our recent work highlights the profound effects of redox signalling by GPx2 KD on the mammary tumour phenotype involving ROS/HIF1α signalling, causing vascular malfunction, resulting in hypoxia and metabolic plasticity." (PMID 38238426, 2024). "Analysis of breast cancer clinical samples from the TCGA database demonstrated a positive association between HIF1α and ALKBH5 mRNA expression." (PMID 38520019, 2024). "KDM1A-driven HIF1A has been associated with aggressive behavior in breast cancer cells, and HIF1A was shown to enhance angiogenesis, cell migration, and colony formation in the Hif1αKA/KA knock-in mouse model." (PMID 39458030, 2024). "In summary, in breast cancer, HIF-1α mainly promotes glycolysis by inducing genes encoding glucose transporters such as GLUT1 and glycolytic enzymes." (PMID 38236337, 2024). "Collectively, these results underscored a dramatic effect of redox signaling on p63 activation by HIF1α, underlying phenotypic and metabolic plasticity leading to mammary tumour metastasis." (PMID 38238426, 2024).
breast cancer (continued). "MMPs, other ECM-associated proteases, integrins, and HIF-1α are promising therapeutic targets for breast cancer." (PMID 39684583, 2024). "One of the first described roles of circRNA in BC was circDENND4C, which is an HIF1α-associated circRNA promoting the proliferation of breast cancer under hypoxia." (PMID 39795985, 2024). "In breast cancer, the overexpression of HIF-1α is often associated with aggressive tumor characteristics." (PMID 38396737, 2024). "It has been reported that the STAT3/HIF-1α pathway is closely associated with the progression of various tumors, including prostate cancer, hepatocarcinoma, breast cancer, and ovarian cancer." (PMID 38990440, 2024). "In breast cancer (BC) cells, alterations in apoptotic activity following HIF-1α activation are associated with increased drug resistance, though the precise mechanisms warrant further investigation." (PMID 38799423, 2024). "For instance, HIF-1α has been associated with growth, metastasis and treatment resistance in breast cancer by activating the PI3K/Akt/mTOR pathway." (PMID 36674861, 2023). "Taken together, these results indicate that metformin can attenuate DPP-4 deficiency-induced breast cancer autophagy and survival through suppression of the mTOR/HIF-1α pathway." (PMID 37760498, 2023). "The primary endothelial response that initiates angiogenic hypoxia signaling in breast cancer and particularly activates tumor-associated macrophages (TAMs) to produce pro-angiogenic cytokines and growth factors involves stable HIF-1α expression." (PMID 37658431, 2023). "The E‐cadhesion formation, HIF‐1α‐mediated decreased senescence and improved tumor stemness were the main causes to drive drug resistance of breast cancer cells." (PMID 37424037, 2023). "In another study, the upregulation of Orai3 together with TRPC1 in breast cancer has been linked to HIF-1α, as its silencing reduced the expression of both channels." (PMID 36612099, 2022). "Tumour HIF-1α-positivity is also associated with increased breast cancer death (HR0–10 years 1.9 [1.2–2.9], p = 0.004)." (PMID 35140341, 2022). "Overexpression of hypoxia-inducible factor-1 alpha (HIF-1α) is associated with drug resistance, poor prognosis, and a higher risk of metastasis in breast cancer patients." (PMID 36003773, 2022). "Many studies have shown that HIF-1α is overexpressed in breast cancer, and HIF-1α has been identified as an independent prognostic factor of breast cancer, and its high expression is significantly associated with poor DFS and OS in breast cancer patients." (PMID 36226050, 2022). "In this large breast cancer material, we establish that HIF-1α positivity is associated with the tumour subtype." (PMID 35140341, 2022). "Overexpression of HIF-1α has been associated with breast cancer metastasis and poor clinical prognosis." (PMID 36080483, 2022). "In contrast, Hif1α deletion in a PyMT mammary cancer model reduced bone metastasis but was associated with increased pulmonary metastasis." (PMID 35646658, 2022). "Several studies have examined the role of HIF-1α as a prognosis factor in breast cancer and have associated HIF-1α overexpression with shorter DFS and OS." (PMID 36358811, 2022). "Hypoxia has been shown to affect cellular activity by stabilizing HIF-1α and HIF-1α, which are linked to distant metastasis and a poor prognosis, and upregulation is more common in breast cancer metastases than in the initial tumor." (PMID 36192752, 2022). "Loss of the antioxidant glutathione peroxidase 2 in breast cancer cells increases reactive oxygen species, thereby activating hypoxia inducible factor-α (HIF1α) signaling." (PMID 35193955, 2022). "Preclinical studies in mouse models have also demonstrated that loss of HIF-1α or HIF-2α expression impairs the metastasis of breast cancer cells to axillary lymph nodes, lungs and bone." (PMID 36230969, 2022).
breast cancer (continued). "The authors robustly support the opposite functions of both TP73 variants in angiogenesis in a HIF1‐α dependent manner and identified angiogenesis and hypoxia signatures in breast cancer patients with high ΔNp73 levels." (PMID 35586989, 2022). "Evidence suggests that ATP and HIF-1α are closely associated with breast cancer chemoresistance as well as drug resistance in multiple other carcinomas." (PMID 35236823, 2022). "Hypoxia-caused activation of SIAH2/HIF-1α pathway in breast cancer SP cells was also repressed by miR-340-5p mimics." (PMID 35309179, 2022). "HIF-1α-stabilizing lncRNA (HISLA) from tumor-associated macrophages regulates aerobic glycolysis in breast cancer cells by inhibiting the hydroxylation and degradation of HIF-1α." (PMID 35002507, 2022). "HIF-1α is upregulated in different breast cancer subtypes and is associated with poor prognosis and drug resistance in breast cancer." (PMID 36003773, 2022). "In sum, the cumulative data point to profound effects of GPx2 loss on mammary tumor progression, resulting in ROS/HIF1α/VEGFA signaling, causing vascular malfunction and hypoxia." (PMID 35193955, 2022). "Previous studies have shown that SLC7A5 is highly expressed in breast cancer, and positively associated with histopathological grade and the expression of proliferation marker Ki-67 and HIF-1α." (PMID 35986300, 2022). "In relapse-free survival (RFS), overall survival (OS), distant metastasis-free survival (DMFS), and post-progression survival (PPS) analyses, high mRNA levels of HIF-1α were associated with lower survival rates in patients with breast carcinoma." (PMID 35236823, 2022). "Another study examined the association between HIF-1α expression and recurrence-free survival in a cohort of premenopausal breast cancer patients from a randomized trial of TAM therapy." (PMID 34736510, 2021). "The levels of HIF-1α have been implicated as an independent prognostic factor for patients with breast cancer." (PMID 34977036, 2021). "Rapid tumor growth and intratumoral hypoxia caused by abnormal tumor vascularity leads to a significantly increased risk of breast cancer metastasis which is mainly mediated by HIF-1α." (PMID 34948213, 2021). "After verification of the diagnostic value of the differential expression of the HIF-1α gene in peripheral blood samples from breast cancer patients, the analysis of its potential as a predictive marker was performed." (PMID 33888756, 2021). "Correspondingly, a reduction of transketolase in breast cancer cells leads to decreased HIF-1α by increasing levels of SDH, FH, and MDM2, causing inhibition of tumor metastasis." (PMID 33637686, 2021). "Extracellular vesicle-packaged HIF-1α-stabilizing lncRNA (HISLA) from tumor-associated macrophages regulates aerobic glycolysis in breast cancer cells by inhibiting the hydroxylation and degradation of HIF-1α." (PMID 34654454, 2021). "In a breast cancer cell model, the knockdown of HIF1α completely abrogated the enhanced release of EVs caused by hypoxia." (PMID 34209290, 2021). "Overall, these findings indicate that UCA1 is a hallmark of hypoxic breast cancer and its expression is positively regulated by HIF-1α." (PMID 34054950, 2021). "In the present study, we investigated the ability of baicalein to resensitize TAM‐resistant breast cancer cells both in vitro and in vivo, and explored the potential mechanisms underlying HIF‐1α–mediated aerobic glycolysis and mitochondrial dysfunction." (PMID 34841716, 2021). "In this study, we evaluated the association between HIF-1α expression and breast cancer recurrence and its association with timing of breast cancer recurrence." (PMID 34736510, 2021). "We evaluated the association of HIF-1α expression with breast cancer recurrence, and its association with timing of breast cancer recurrence." (PMID 34736510, 2021). "C1QBP levels were associated with the expression of VCAM-1, P65 and HIF-1α in patients with breast cancer patients, especially in TNBC." (PMID 33708767, 2021).